GIT1 (GIT ArfGAP 1)
Diseases named in the same sentence as GIT1 in open-access papers (continued):
Sharing a sentence is not in itself a finding about the gene and the disease.
preeclampsia (2 papers, 2018 to 2023). Preeclampsia is a hypertensive disorder of pregnancy that is characterized by new-onset hypertension with proteinuria presenting after 20 weeks of gestation, and depending on mild or severe forms may initially present with severe headache, visual disturbances, and hyperreflexia. "In this study, we aimed to understand the role of GIT1 in sFlt-1–induced preeclampsia phenotype in pregnant mice and to elucidate the underlying mechanisms." (PMID 30135105, 2018). "In a rat model of preeclampsia, GIT1 knockdown can inhibit the activity of eNOS in the placenta and induce the exacerbation of the preeclampsia phenotype." (PMID 37256221, 2023). "Altogether, these data suggest that overexpression of GIT1 attenuates sFlt-1-induced preeclampsia symptoms." (PMID 30135105, 2018). "We overexpressed GIT1 in pregnant C57BL/6 mice by injection of adenovirus to further identify the effects of GIT1 on preeclampsia." (PMID 30135105, 2018). "Here, we extend these findings by exploring the function of GIT1 in regulating eNOS activity in sFlt-1–induced preeclampsia mice." (PMID 30135105, 2018). "Our findings suggest that GIT1 significantly extenuates the sFlt-1-induced preeclampsia phenotypes by inhibiting eNOS activity, indicating a crucial role of GIT1 in the progression of preeclampsia." (PMID 30135105, 2018). "However, more detailed molecular mechanisms of how GIT1 regulates eNOS activity in preeclampsia mice still need to be further elucidated." (PMID 30135105, 2018). "Our findings might molecularly explain the mechanism that GIT1 alleviates sFlt-1-induced preeclampsia symptoms by regulating NO production and eNOS activity." (PMID 30135105, 2018). "Additional GIT1 attenuates sFlt-1-induced preeclampsia phenotypes." (PMID 30135105, 2018). "The aim of this paper is to investigate the effect of GIT1 on preeclampsia." (PMID 30135105, 2018). "Thus, in our study, we used adenovirus to overexpress sFlt-1 for inducing preeclampsia in mice and explored the function of GIT1 in monitoring sFlt-1-induced preeclampsia phenotype." (PMID 30135105, 2018). "Although future studies could be made to further reveal the specific molecular mechanisms of how GIT1 aggravates the sFlt-1–induced preeclampsia-like phenotype by regulating NO/eNOS pathway, our research provides reliable clues and basis for the follow-up study on preeclampsia." (PMID 30135105, 2018). "In conclusion, our data demonstrate that absence of GIT1 exacerbates the preeclampsia-like phenotypes induced by the overexpression of sFlt-1 in pregnant female mice." (PMID 30135105, 2018).
schizophrenia (2 papers, 2017 to 2022). A major psychotic disorder characterized by abnormalities in the perception or expression of reality. "GIT1, a gene that regulates actin filament dynamics associated with schizophrenia, can bind to Rac/Cdc42 and interacts with PAKs." (PMID 33306168, 2022). "Most schizophrenia cases carrying GIT1 variants fail to induce PAK3 activation and GAD1, the key enzyme in GABA biosynthesis, in neurons, suggesting the contribution of PAK3 dysregulation in the synaptic deficits in schizophrenia." (PMID 33306168, 2022). "Git1 point mutations associated with schizophrenia show defects in PAK3 (p21 protein (Cdc42/Rac)-activated kinase 3) and MAPK (mitogen-activated protein kinase) activation and signaling." (PMID 29150658, 2017).
triple-negative breast carcinoma (2 papers, 2017 to 2020). An invasive breast carcinoma which is negative for expression of estrogen receptor (ER), progesterone receptor (PR), and human epidermal growth factor receptor 2 (HER2). "Interestingly, these data align closely with data for other GEFs such as GIT1 which when silenced via siRNA (or indeed miR-149) was shown to decrease invasion and metastases in the setting of triple negative breast cancer." (PMID 33256106, 2020).
coronary artery disease (1 paper, 2020). "Similarly, QTLs for genes linked to coronary artery disease risk (e.g. LPL, SREBF1, GIT1, SKIV2L, MAP3K11/MLK3) were associated with colocalization sites linking coronary artery disease with mean platelet volume, lymphocyte, and/or reticulocyte counts." (PMID 32600345, 2020).
glioblastoma (1 paper, 2025). The most malignant astrocytic tumor (WHO grade IV). "The different regulatory roles of GIT1 and GIT2 in microtubule nucleation are highlighted by differential subcellular distribution of their tagged variants in diverse glioblastoma cell lines." (PMID 40176062, 2025). "In this study, we show that the depletion of GIT2 in glioblastoma cells has a more pronounced and opposite effect on centrosomal microtubule nucleation compared to GIT1." (PMID 40176062, 2025). "While the depletion of GIT1 and GIT2 has diverse effects on centrosomal microtubule nucleation, the depletion of either GIT1 or GIT2 resulted in the inhibition of glioblastoma cell migration, as demonstrated by a wound healing assay." (PMID 40176062, 2025). "Whether GIT1 and GIT2 also exhibit regulatory effects on microtubule nucleation in glioblastoma cells with elevated levels of γ-tubulin, both at the transcript and protein levels, remains unclear." (PMID 40176062, 2025). "While GIT proteins (GIT1 and GIT2) regulate both cell migration and microtubule organization, their corresponding regulatory mechanisms in glioblastoma cells remain largely unknown." (PMID 40176062, 2025). "To determine whether GIT1 and GIT2 exhibit regulatory effects on microtubule nucleation in human glioblastoma cells, characterized by enhanced expression of both γ-tubulin isoforms, we first conducted immunoprecipitation experiments using whole-cell extracts from U-251 MG glioblastoma cells." (PMID 40176062, 2025).
ischemia (1 paper, 2022). A hypoperfusion of the BLOOD through an organ or tissue caused by a PATHOLOGIC CONSTRICTION or obstruction of its BLOOD VESSELS, or an absence of BLOOD CIRCULATION. "The GIT1 protein can regulate the level of mitochondrial autophagy during neuronal ischemia-reperfusion by regulating the phosphorylation of Beclin-1 to protect neurons during spinal cord ischemia-reperfusion." (PMID 35340202, 2022).
neuroblastoma (1 paper, 2023). Neuroblastoma (NB) is the most common solid, extracranial childhood tumor. "This interaction was verified in mammalian cells and the hippocampus and neocortex in the rat brain, and PTN increased tyrosine phosphorylation of GIT1/Cat-1 in B103 neuroblastoma and mouse oligodendrocyte-lineage OL1 cells." (PMID 37175798, 2023).
prostate carcinoma (1 paper, 2021). A carcinoma that arises from epithelial cells of the prostate gland. "It is reported that GIT1 expression is upregulated and is a biomarker for tumor prognosis in lung, oral, gastric, breast, colorectal, esophagus and prostate cancers." (PMID 34663332, 2021).
urothelial bladder carcinoma (1 paper, 2021). "Scholars have reported that EZH2 can repress multiple downstream targets (e.g., KDM6A, GIT1) directly by binding to their promoter regions contributed to the progression of urothelial bladder carcinoma." (PMID 34776951, 2021).
cancer (20 papers, 2015 to 2026). A tumor composed of atypical neoplastic, often pleomorphic cells that invade other tissues. "ARF6 (GAPs), such as SMAP1, AMAP1 and GIT1, are also linked to cancer progression." (PMID 35143561, 2022). "Of nine compounds tested, compound 3 (C3) selectively interacts with GIT1 and shows an anti-cancer effect in a GIT1-dependent manner." (PMID 41720764, 2026). "miR-491 was demonstrated to be a potential target for the therapy of HCCs, since it can decrease cancer stem cells-like properties of HCC by inhibition of GIT-1/NF-κB-mediated EMT." (PMID 37953323, 2024). "Among 28 pairs HCC tissue and adjacent non-cancer tissues, the RNA expression level of GIT1 was found to be up-regulated in 22 pairs (78.6%)." (PMID 33258389, 2021). "Our orthotopic metastatic model demonstrated that GIT1 expression is important in promoting cancer cell metastasis from the primary sites." (PMID 26462147, 2015). "G-protein-coupled receptor kinase interacting protein 1 (GIT1) is participated in cell movement activation, which is a fundamental process during tissue development and cancer progression." (PMID 26462147, 2015). "According to our in vitro functional assays, GIT1 regulates cancer cell mobility through Rac1/Cdc42 activation in NSCLC cells." (PMID 26462147, 2015). "This raises the possible correlations and importance between GIT1 and Rac1/Cdc42 in regulating cancer progression." (PMID 26462147, 2015). "Two recent studies showed that GIT1 (G protein-coupled receptor kinase interacting ArfGAP 1), an important scaffold protein for focal adhesion complexes, plays an important role in cancer cell migration/invasion and metastasis." (PMID 25614041, 2015). "The finding of distinct cancer types with different miRs targeting the same substrate GIT1 to inhibit metastasis implies the important role of this molecule in cancer cell migration/invasion and metastasis." (PMID 25614041, 2015). "Several studies have revealed the involvement of GIT1 in the development and progression of cancer, including cell transformation, growth and migration." (PMID 26462147, 2015). "Evidence has shown that GIT1/β-Pix function was highly correlated with cancer development and metastasis in a wide spectrum of human malignancies including gastric cancer, but its exact functional roles were largely unknown." (PMID 36418900, 2022). "These GIT1 properties enhance its involvement in cancer occurrence and development." (PMID 33258389, 2021). "In different cancer cell types, GIT1, S6K1, and PFKFB3 have been identified as targets of PKD3." (PMID 34145024, 2021). "Furthermore, recent studies have indicated that miR-149-5p has a tumor-suppressive role in the regulation of cancer cell growth in human cancer through modulating GIT1, circNRIP1, and HNF1A-AS." (PMID 33924142, 2021). "Paxillin, GIT1, and p190RhoGAP are key regulators of focal adhesion turnover and invadosome formation, all of which are crucial for the motility and invasiveness of cancer cells." (PMID 26857455, 2016). "Although the importance of Rac1/Cdc42 activation is well documented in cancer aggressiveness, the clinical importance of GIT1 remains largely unknown." (PMID 26462147, 2015). "In addition, GIT1 also plays an important role in other malignant tumors." (PMID 33258389, 2021). "However, the role of GIT1 in cancer invasiveness and metastasis is relatively less understood." (PMID 26462147, 2015). "However, the clinical significance of GIT1 in cancer prognosis and patient survival remains unclear." (PMID 26462147, 2015). "GIT1 could be directly targeted by miR-149 and miR-491-5p in the different context of cancer cells." (PMID 25614041, 2015). "The expression levels of GIT1 in HCC tissues and other cancers was determined by using the Oncomine and TCGA databases." (PMID 33258389, 2021). "GIT1, which inactivates ARF6 specifically, is highly expressed in several types of cancers, including breast, cervical, colon and liver." (PMID 32426352, 2020).
cancer (continued). "GIT1 and GIT2 are key regulators of focal adhesion turnover and cell motility in cancer cells." (PMID 40176062, 2025). "Moreover, GIT1 interacts with Paxillin and p21-activated kinase Interacting eXchange factor (PIX) at FAs, regulating cancer cell migration." (PMID 32426352, 2020). "Consistent with studies in nontransformed cells, we found that GIT1 is phosphorylated in an SRC-dependent manner in cancer cells." (PMID 30559289, 2019). "Therefore, we assume that these compounds, or other strategies targeting GIT1/β-Pix, have the potential to prevent post-surgery metastasis, which is a frequent occurrence in cancer patients that have no accepted interventive therapeutics." (PMID 36418900, 2022). "Although GIT1 is associated with several types of cancer, it is not clear whether ARF6 inactivation by GIT1 is a requirement for cancer progression." (PMID 32426352, 2020). "Furthermore we analyzed the effect of miR-149 overexpression in two HCC cell lines, HepG2 and MHCC97H, on the expression of PPM1F and other putative target genes (GIT1, SP1, FOXM1) previously reported by other groups to promote migration and invasion in other cancer cell lines." (PMID 26498692, 2015). "GIT1 repressed SRC-mediated YAP/TAZ activity in each of the six cell lines we tested, suggesting that this regulatory mechanism is not unique to one cell line or cancer type." (PMID 30559289, 2019).
tumor (20 papers, 2010 to 2025). "In summary, these data indicated that high levels of GIT1 protect against the initiation of tumour growth through attenuation of Notch signalling and that loss of GIT1 leads to accelerated tumour formation via elevated Notch signalling." (PMID 35318302, 2022). "To explore GIT1’s ability to influence tumour development and growth, we searched for genes associated with cell tumour stemness in breast cancer." (PMID 35318302, 2022). "Clinical significance analysis showed that GIT1 was associated with tumor size and embolus, and HCC patients with GIT1low expression exhibited longer survival outcomes than those with GIT1high." (PMID 33258389, 2021). "We evaluated the association of GIT1 expression in the primary tumour and in the synchronous LN with clinical features and disease aggressiveness." (PMID 29862012, 2017). "We observed that over a third of cases displayed a spatial intratumoural heterogeneous pattern of GIT1 expression between the primary tumour and the lymph node, with loss of GIT1 expression in lymph nodes being more common than its gain." (PMID 29862012, 2017). "We observed that loss of GIT1 expression in the tumour cells of the metastasis was associated with a shorter time to recurrence, poorer overall survival, and a shorter median survival time." (PMID 29862012, 2017). "High GIT1 protein expression was associated with poor tumor histology (well: 63.9% (23/36); moderate: 94.4% (17/18); poor: 90.9% (20/22))." (PMID 28759023, 2017). "Our animal studies with xenografted tumours showed that knockdown of GIT1 expression accelerated the development and growth of the primary tumour." (PMID 35318302, 2022). "In xenograft experiments, overexpression of GIT1 in ER(-) cells prevented or reduced Notch-driven tumour formation." (PMID 35318302, 2022). "Increased GIT1 expression abrogated or reduced the development of tumours in mouse xenograft models via downregulation of Notch activity." (PMID 35318302, 2022). "We further analysed the influence of the Notch-GIT1 axis on tumour development by a limiting dilution assay." (PMID 35318302, 2022). "Immunostaining and flow cytometry revealed that the nuclear Notch1 ICD and Hey1 levels, respectively, were enhanced in the GIT1 knockdown tumours compared to the control tumours." (PMID 35318302, 2022). "Growth curves also showed that GIT1 knockdown and overexpression had a profound effect on tumour growth rates in vivo (doubling time: 2.60-fold increase for GIT1-mRFP, 2.16-fold decrease for GIT1-shRNA3)." (PMID 35318302, 2022). "Among twenty MDA-MB-231 implants, only one GIT1-overexpression tumour was detected, which required 63 days for initiation and 105 days to achieve a size of 0.1 mm3." (PMID 35318302, 2022). "The number of EdU-positive cells in the GIT1 knockdown tumours was significantly higher than in the controls." (PMID 35318302, 2022). "Excitingly, GIT1 overexpression substantially reduced tumour formation in these animals (MDA-MB-231 implants, Ctrl-shRNA versus GIT1-mRFP, P < 0.0001, log-rank test)." (PMID 35318302, 2022). "In MDA-MB-231 cells with elevated GIT1 levels, tumour formation was nearly abolished, and only one small tumour was recorded after 105 days." (PMID 35318302, 2022). "GIT1 expression was significantly correlated with gender (p = 0.019), tumor size (p = 0.023), and embolus (p = 0.002)." (PMID 33258389, 2021). "Univariate analysis showed that tumor size (p < 0.001), numbers (p = 0.042), embolus (p = 0.021), and GIT1 expression (p < 0.001) were predictors of OS." (PMID 33258389, 2021). "Evaluation of GIT1 protein levels in 8 pairs of HCC tumor tissues and adjacent tissues using western blot showed that GIT1 levels were significantly high in HCC tissues (p = 0.003)." (PMID 33258389, 2021). "Tumor size (p = 0.003), capsulation (p = 0.011), and GIT1 expression (p < 0.001) were predictors of cumulative recurrence." (PMID 33258389, 2021).